ENTPD6 (ectonucleoside triphosphate diphosphohydrolase 6)
Description:
Catalyzes the hydrolysis of nucleoside triphosphates and diphosphates in a calcium- or magnesium-dependent manner. Has a strong preference for nucleoside diphosphates, preferentially hydrolyzes GDP, IDP, and UDP, with slower hydrolysis of CDP, ITP, GTP, CTP, ADP, and UTP and virtually no hydrolysis of ATP. The membrane bound form might support glycosylation reactions in the Golgi apparatus and, when released from cells, might catalyze the hydrolysis of extracellular nucleotides.
Synonyms: CD39L2; IL6ST2; NTPDase-6; dJ738P15.3; IL-6SAG
Tractability: Antibody: UniProt places it where antibodies can reach, with high confidence; its Gene Ontology location is reachable by antibodies, with high confidence; UniProt predicts a signal peptide or a membrane-spanning region. PROTAC: ubiquitination databases record sites on it; its protein half-life has been measured.
Gene: Protein-coding gene on chromosome 20 (25,195,693 to 25,228,075, forward strand). Ensembl gene ENSG00000197586.
Subcellular location: Golgi apparatus membrane; Secreted; Cell membrane
Subcellular location (Human Protein Atlas): Golgi apparatus; Predicted to be secreted
Pathways (Reactome):
Metabolism: Phosphate bond hydrolysis by NTPDase proteins
Gene Ontology:
Molecular function: CDP phosphatase activity; GDP phosphatase activity; IDP phosphatase activity; nucleoside diphosphate phosphatase activity; UDP phosphatase activity; guanosine-5'-triphosphate,3'-diphosphate diphosphatase activity; hydrolase activity; ribonucleoside triphosphate phosphatase activity
Biological process: response to calcium ion; response to magnesium ion
Cellular component: extracellular region; Golgi apparatus; plasma membrane; Golgi membrane; cell surface
Genetic constraint (gnomAD): Loss-of-function variants: 44 observed, 59.62 expected, observed/expected ratio (o/e) 0.74, 90% interval 0.58 to 0.95. The upper end of that interval is the gene's LOEUF score, 0.95, which puts it in group 4 of 6, group 1 being the genes least tolerant of losing a copy. Missense variants: 565 observed, 592.12 expected, observed/expected ratio (o/e) 0.95, 90% interval 0.89 to 1.02. Synonymous variants: 239 observed, 240.7 expected, observed/expected ratio (o/e) 0.99, 90% interval 0.89 to 1.11.
Homologues: Orthologues: chimpanzee ENTPD6 (99% identical), mouse Entpd6 (82% identical), rat Entpd6 (81% identical), dog ENTPD6 (81% identical), guinea pig ENTPD6 (78% identical), rabbit ENTPD6 (77% identical), pig ENTPD6 (76% identical), tropical clawed frog entpd6 (49% identical), zebrafish entpd6 (48% identical), Drosophila melanogaster NTPase (33% identical), Caenorhabditis elegans uda-1 (30% identical). Paralogues in human: ENTPD5 (42% identical), ENTPD4 (27% identical), ENTPD7 (26% identical), ENTPD2 (23% identical), ENTPD3 (21% identical), ENTPD1 (20% identical), ENTPD8 (20% identical).
Diseases named in the same sentence as ENTPD6 in open-access papers:
ENTPD6 is named in the same sentence as 6 diseases in open-access papers, as found by Europe PMC text mining. Sharing a sentence is not in itself a finding about the gene and the disease. The quoted sentences say what the papers report.
Azoospermia (2 papers, 2015 to 2023). Absence of any measurable level of sperm,whereby spermatozoa cannot be observed even after centrifugation of the semen pellet. "A genome-wide association study on non-obstructive azoospermia (NOA) indicated that ENTPD6 may be a novel meiosis-associated gene responsible for NOA after functional screening, which suggested the role of this gene in spermatogenesis." (PMID 37020555, 2023).
COVID-19 (1 paper, 2023). A disease caused by infection with severe acute respiratory syndrome coronavirus 2. "It was revealed that three hub CORGs (ENTPD6, CIB1, and EIF3B) had good diagnostic performance to discriminate COVID-19/MI and control samples (AUC > 0.75)." (PMID 37020555, 2023).
cancer (1 paper, 2026). A tumor composed of atypical neoplastic, often pleomorphic cells that invade other tissues. "In contrast, despite comparable functionality, the related ENTPD6 shows relatively stable expression across tissues in both normal and pathological conditions, with specific roles in cancer yet unclear." (PMID 41685236, 2026).
tumours (1 paper, 2025). "Moreover, we identified five molecules (SCGB1B2P, SFRP2, POSTN, COL3A1, ENTPD6) that were universally overexpressed in medullary cells infiltrated by IBC tumours." (PMID 40624675, 2025).
ENTPD6 also shares sentences with these, for which no sentence is quoted: heart failure (1 paper); Obesity (1).